CCL2 (C-C motif chemokine ligand 2)
Diseases named in the same sentence as CCL2 in open-access papers (continued):
Sharing a sentence is not in itself a finding about the gene and the disease.
tumor (continued). "MCP-1 (chemokine ligand 2/CCL2), a pivotal member of the CC chemokine superfamily, orchestrates tumor-stromal interactions by dually modulating neoplastic proliferation and angiogenic programming." (PMID 40382743, 2025). "Perhaps in the future, emphasis can be placed on developing synergistic therapies that inhibit CCL2 and other chemokine-based tumor-targeted drug carriers." (PMID 41445742, 2025). "It has been demonstrated that alveolar and interstitial macrophages in the lungs can uptake tumor microparticles and secrete CCL2." (PMID 40427136, 2025). "On the basis of these results, we established that TMBIM1 modulates tumor CCL2 and PD-L1 expression through the regulation of YBX1." (PMID 40083936, 2025). "These recruited TAMs secrete high levels of CCL2 and IL-6, which act on tumor cells via CCR2 and IL-6R, respectively." (PMID 40963633, 2025). "GBM cells and tumor-associated endothelial cells secrete CCL2, which binds to CCR2 on circulating CX3CR1+CCR2+ monocytes, facilitating their transmigration across the blood–brain barrier into the tumor microenvironment." (PMID 41002423, 2025). "To functionally validate the CCL2-TAMs recruitment axis identified above, we developed a 3D Cal-27 tumor spheroid-macrophage co-culture system." (PMID 40808689, 2025). "We also found an upregulation of CCL2 (P < 0.01), suggesting macrophage infiltration and accentuated tumor endothelial-mesenchymal transition as well as increased mRNA expression of TNF (P < 0.01)." (PMID 39305371, 2025). "Inhibition of CCL2 signaling has been shown to suppress tumor growth and metastasis in various experimental models.1029–1033 However, concerns have arisen regarding the long-term efficacy of this approach." (PMID 40055311, 2025). "Chemokine ligand 2 (CCL2) is a key regulatory molecule in the tumor microenvironment (TME) participating in the occurrence, progression, and metastasis of tumors through complex mechanisms." (PMID 41341593, 2025). "To clinically evaluate the expression levels of PDPN, CD31, and CCL2 in GC samples, we assessed protein levels in 400 tumor and 73 normal gastric tissue samples." (PMID 39764562, 2025). "It is secreted by tumor cells together with other chemokines such as CCL2, inducing TAMs infiltration and promoting cancer progression." (PMID 39996747, 2025). "By quantitative PCR (qPCR), we confirmed that Il1a, Ccl2, and Ccl3 mRNAs were virtually undetected in the tumor cells but were expressed predominantly in the CD45+ hematopoietic cells and, to a lesser degree, in the VE-cadherin+GFP– endothelial cells." (PMID 40131370, 2025). "Chemokine CCL2 is implicated in MDSC infiltration into the GBM microenvironment, enabling tumor-recruiting by CCR2+ cells." (PMID 40514725, 2025). "The coordinated action of TNF-α and IL-1β leads to a sustained CCL2 release from tumor and endothelial cells." (PMID 41341593, 2025). "As THBS1 and BMPs are already known to promote tumor dormancy, we continued to investigate the role of PEAR1 and the chemokine CCL2 in endothelium-mediated induction of dormancy of various other tumor cell types." (PMID 41185039, 2025). "Cardamonin’s effect on PD-L1 and CCL2 expressions suggests that it can lower PD-L1 levels and reduce tumor resistance over time by inhibiting CCL2." (PMID 40940890, 2025). "CCL2 (MCP‐1) acts like a siren and lures hepatic stellate cells (HSC), the precursors of cancer‐associated fibroblasts (CAF), into the tumor." (PMID 40145607, 2025). "Within the tumor microenvironment (TME), tumor-associated macrophages predominantly adopt an M2-like phenotype, secreting cytokines such as IL-10 and TGF-β, chemokines like CCL2 and CCL5, and proteases such as matrix metalloproteinases (MMPs)." (PMID 40487409, 2025). "CCL2’s distinct mechanisms for regulating the TIME are controlled by the tumor, tumor-infiltrating immune cells, and the tumor stroma." (PMID 40940890, 2025).
tumor (continued). "Considering the role of chemokines in TAM recruitment, the inactivation of retinoblastoma (RB), a tumour suppressor gene, enhances the secretion of CCL2, promoting tumour microenvironment by the recruitment of TAMs." (PMID 40852716, 2025). "CC chemokines such as CCL1, CCL2, CCL3, CCL21 and CCL25 are also associated with invasion and migration in many tumours." (PMID 40852716, 2025). "Chemokines under NF-κB control, including CCL2 and CXCL8, orchestrate the recruitment of myeloid-derived suppressor cells (MDSCs) and tumor-associated macrophages (TAMs), sustaining chronic inflammation and amplifying immunosuppressive circuits." (PMID 41035656, 2025). "CAFs recruit MDSCs from the bone marrow to the tumor site by secreting cytokines such as CCL2, CSF-1 and IL-6." (PMID 40934009, 2025). "IQGAP1 interacts with MYL9 and acts on the ERK1/2 pathway to regulate cancer-associated fibroblasts (CAFs), which secrete CCL2 and TGF-β1, thereby influencing the tumor microenvironment and patient outcomes." (PMID 41035668, 2025). "A potential mechanism involved the recruitment of monocytes from the bloodstream to tumor tissue via a gradient of CCL2 cytokine secreted by TME, followed by their differentiation into macrophages." (PMID 40303994, 2025). "Conversely, changes in the expression of CCL2, CCL5, and CCL21 were linked to tumor stages, influencing tumor growth and metastasis by modulating immune cell activity, thereby highlighting their value as therapeutic targets." (PMID 39859340, 2025). "Tumor-derived cytokines such as IL-6, IL-8, IL-10, CSF-1, CCL2, CXCL2, PGE2 and TGF-β promote MDSC expansion and recruitment, whereas hypoxia shifts MDSC metabolism toward fatty acid oxidation, reinforcing their immunosuppressive properties." (PMID 40628732, 2025). "CCL2 provides support for tumor cell metastasis by not only activating and recruiting immunosuppressive cells, but also by directly inhibiting immune cell activity, upregulate the expression of immune checkpoints, acting together on the formation of the PMN." (PMID 41341593, 2025). "For instance, co-culture with CC chemokine ligand 2 (CCL2) has been shown to increase tumor proliferation." (PMID 40724900, 2025). "Next, active TAFs are fed back to tumor cells through the secretion of CCL2 and its receptor CCR2 on the membrane of LGALS3+ cells." (PMID 40600063, 2025). "IL-6, a pivotal tumor-promoting cytokine, induces CCL2 secretion via STAT3 activation; the two engage in macrophage-mediated feedback amplification." (PMID 41341593, 2025). "CCL2, produced by tumor cells and various host microenvironment components like adipocytes, can directly stimulate cancer cells and bolster proliferation through the PI3K-AKT phosphorylation pathway." (PMID 40520902, 2025). "In conclusion, elevated glycolysis levels in PDAC promote ENSA-K63la, a crucial step that triggers STAT3/CCL2 signaling in tumor cells." (PMID 39883522, 2025). "The high levels of CCL2 are also in accordance with an increase in PD-L1+ myeloid tumor-infiltrating cells, indicating a potential mechanism through which HNSCC evades immune surveillance." (PMID 40860824, 2025). "In theory, CCL2 blockade can simultaneously inhibit the recruitment of immunosuppressive cells and enhance the infiltration of killer T cells to achieve tumor suppression, but the clinical benefit of targeting the CCL2/CCR2 axis is still pending." (PMID 41341593, 2025). "It promotes the M2 polarization and infiltration of TAMs by CCL2, and then promotes tumor cell proliferation, migration, invasion and EMT." (PMID 41341593, 2025). "A coculture model of PAAD cells and pancreatic stellate cells revealed that Gal-3 mediated the Ca2+/−calcineurin–NFAT pathway to increase the transcription of CCL2 and BSG in tumor-associated fibroblasts." (PMID 40600063, 2025). "It targets TNS3 and PXN in macrophages, while also regulating CCL2 expression in tumor cells, creating a supportive niche for tumor progression." (PMID 40647470, 2025).
tumor (continued). "Specifically, it is believed that chemokine (C-C motif) ligand 2 (CCL-2) plays a major role in recruiting cells such as M2 macrophages to the tumor site." (PMID 40723152, 2025). "In conclusion, CCL2 acts as a core driver of tumor metastasis by regulating EMT, ECM degradation, vascular leakage, and premetastatic niche formation." (PMID 41341593, 2025). "Bioinformatics and 3D models identified CCL2 as a gefitinib-induced chemokine reversed by FMD, which suppressed CCL2-mediated TAMs recruitment and tumor spheroid growth." (PMID 40808689, 2025). "In summary, tumor-derived chemokines like CCL2 and CCL3 recruit MDSC precursors, macrophages, and DCs in OSCC." (PMID 41445742, 2025). "Our findings showed the important function of CCL2+ macrophages in orchestrating a favorable tumor microenvironment." (PMID 40092486, 2025). "In vivo, combined FMD and gefitinib treatment significantly reduced tumor volume, Ki-67+ proliferating cells, and M2-like TAMs density, accompanied by decreased serum CCL2 levels." (PMID 40808689, 2025). "In melanoma, tumor cells secrete substantial amounts of CCL2, attracting monocytes and inducing their differentiation into M2-type macrophages, which promote tumor growth and immunosuppression." (PMID 41346595, 2025). "It further highlights Lcn2+ neutrophils and Ccl2+ fibroblasts as potential therapeutic targets for improving CAR-T cell anti-tumor efficacy." (PMID 40568084, 2025). "Among cytokines, C-C Motif Chemokine Ligand 2 (CCL2) is produced by tumor cells and a variety of other cells in the host microenvironment, including adipocytes." (PMID 40520902, 2025). "Cytokines play a pivotal role in regulating circulating immune cells, and CCL2 is known to recruit macrophages and immunosuppressive cells to the tumor microenvironment." (PMID 39749673, 2025). "CCL2 as a pro-inflammatory molecule is an essential recruiter of macrophages to both adipose tissue and tumor microenvironment." (PMID 40076892, 2025). "Chemokines such as CXCL12, CXCL5 and CCL2 regulate tumor metabolism and promote a metabolic shift toward enhanced glycolysis and lipid metabolism to support rapid tumor growth, even under hypoxic conditions." (PMID 40134607, 2025). "Taken together, both Ccr1- and Ccr2-dependent recruitment and stimulation of monocytes/macrophages promote metastasis, which are increased by tumor-derived Ccl2." (PMID 39566333, 2025). "Regarding sensory fibers, it has been observed that their stimulation by melanoma tumor cells induces the expression of proinflammatory cytokines, such as CCL2, CCL3, CCL5, which speed up MDSC recruitment and tumor growth." (PMID 41306965, 2025). "GBM tumor cells and associated myeloid populations produce immunomodulatory factors such as indoleamine 2,3-dioxygenase (IDO), CCL2, and CCL22, which contribute to the recruitment and regulation of T cell populations within the tumor microenvironment." (PMID 40867165, 2025). "By promoting the recruitment of immunosuppressive immune cells such as TAMs and Treg cells, CCL2 contributes to tumor immune escape." (PMID 41376630, 2025). "This functional interdependence between immune microenvironment remodeling and tumor growth kinetics suggests CCL2-mediated chemotaxis constitutes a critical resistance mechanism." (PMID 40808689, 2025). "IL-1β, another proinflammatory cytokine belonging to the IL-1 family, promotes CCL2 expression in macrophages and tumor cells within the TME." (PMID 41341593, 2025). "When using AKT inhibitors perifosine and LY294002, both HUVECs treated with CCL2 and tumor‐burdened mice injected with PDPN(+) CAFs and GC cells maintained their proangiogenic properties." (PMID 39764562, 2025). "Granulocyte myeloid-derived suppressor cells (g-MDSC’s) are recruited by IL-8, GM-CSF, TNF-alpha, YAP1, CXCR2, and CCL2, conferring tumor immunotherapy resistance to CRC." (PMID 40777019, 2025).
tumor (continued). "Strategies to overcome resistance involve combining ICIs with natural compounds, such as silibinin, to enhance immunogenicity and targeting stromal interactions, e.g., the CCL2/CCR2 axis and decreased tumor-associated macrophage (TAM) recruitment." (PMID 40650040, 2025). "Functional studies using BM chimeras revealed that hematopoietic deletion of Ccl2 significantly reduced both tumor burden and the presence of extravascular recMacs, demonstrating that macrophage-intrinsic CCL2 promotes tumor progression." (PMID 40630529, 2025). "High levels of CCL2 promote polarization of tumor microenvironment macrophages to the phenotype of TAMs and enhance the interaction between them and tumor cells." (PMID 39996747, 2025). "The CCL2-induced CCL3 cascade also prolongs the retention time of MAMs at the tumor site, thereby accelerating the extravasation of tumor cells." (PMID 41341593, 2025). "Chemokines, including Ccl2, can also promote the presence and activation of macrophages at the metastatic sites, facilitating tumor cell extravasation and metastasis." (PMID 39566333, 2025). "Tumour-derived CCL2 also stimulates neutrophil production of hydrogen peroxide (H2O2), restricting metastatic spread." (PMID 41451221, 2025). "Given that gefitinib, TAMs, and CCL2 are all interconnected with tumor vascularization processes, it is plausible that FMD influences gefitinib’s anti-angiogenic effect." (PMID 40808689, 2025). "For example, the upregulation of CCL2 induced by LNMAT1 can attract macrophages to the tumor, promoting lymphatic metastasis through VEGF-C secretion." (PMID 40745648, 2025). "WNT5a, categorized as a non-canonical WNT ligand, triggers pathways such as CaMKII-ERK, resulting in the release of tumor-promoting substances like CCL2." (PMID 41041337, 2025). "Analysis of the isolated and homogenized tumor samples revealed that the intratumoral levels of CCL2 and PD-L1 were notably elevated in the TMBIM1-OE tumors." (PMID 40083936, 2025). "In one proposed model, circulating progenitor cells of AMs are recruited to the tumor site by CCL2, which is secreted by interstitial macrophages." (PMID 40051246, 2025). "Crosstalk with tumor cells through exosomes and soluble factors (e.g., CCL2, CSF-1) reprograms TAMs toward pro-tumor phenotypes." (PMID 40422244, 2025). "During tumor development, inflammatory signals recruit macrophages to the tumor stroma, including chemokines (e.g., CCL2, CCL5, CXCL12), cytokines (e.g., VEGF, CSF1), and complement factors." (PMID 40872551, 2025). "Recently, our group reported that tumor hypoxia induces CCL-2 secretion by primary BMMCs in a calcium-dependent manner." (PMID 40362499, 2025). "CCL2 also exerts TAM-independent effects on tumor cells and the TME, such as recruiting other myeloid subsets and non-myeloid cells, which sustains an immunosuppressive environment, stimulates tumor cell growth and motility, and further promotes angiogenesis." (PMID 39930476, 2025). "Lactate has also been shown to stimulate the release of interleukin (IL)-1β from TAMs in an inflammatory vesicle-dependent manner, with IL-1β further promoting TAM recruitment through the induction of C-C motif chemokine ligand 2 from tumor cells." (PMID 40165895, 2025). "It is known that PBMC recruitment plays essential roles in tumor progression and metastasis and that cancer cells are able to recruit them by secreting several chemokines, such as CCL2, CCL3, CCL4, and CCL5 among many others." (PMID 40112045, 2025). "In a mouse model of breast cancer undergoing treatment with doxorubicin and cisplatin, tumor cells in the microenvironment can attract CCR2+ macrophages by releasing CCL2." (PMID 41041337, 2025). "CCL2, secreted by tumor and stromal cells, recruits CCR2+ monocytes, promoting TAM differentiation; anti-CCL2 antibodies reduce TAM infiltration and tumor progression." (PMID 40936918, 2025).
tumor (continued). "Tumor cells can continuously and autonomously secrete CCL2 through intrinsic mechanisms due to intrinsic gene or mutation or epigenetic changes without external stimulation." (PMID 41341593, 2025). "CCL17 and CCL22 promote the homing of Tregs to the lungs, whereas CCL2 is required for the recruitment of Tregs to tumor sites." (PMID 39740041, 2025). "M-MDSCs, along with monocytes, are predominantly drawn to the tumor by chemokines secreted by the tumor cells, including CCL2, CCL5, and CSF1." (PMID 40722739, 2025). "This approach triggers c-Jun-dependent IL-12 production and CCL2-mediated plasmacytoid DC recruitment, enabling localized and systemic tumor suppression." (PMID 40547481, 2025). "Because of this, CCL2 overexpression can induce tumor metastasis, invasion, and the development of immune resistance, and in cancer patients, it characterizes a poor prognosis due to immunosuppressive cell subtype accumulation." (PMID 40940890, 2025). "Conversely, CCL2 knockdown significantly reduces macrophage densities, tumor proliferation, skin erythema, and metastasis, highlighting the critical role of CCL2 in macrophage expansion and, consequently, tumor growth." (PMID 40940890, 2025). "Previous studies have shown that tumor-derived CCL2 promotes the recruitment of TAMs and MDSCs, while CXCL1 promotes the recruitment of MDSCs." (PMID 41282257, 2025). "Chemoattractants released by OV-infected tumor cells, such as CCL-2 and CCN1, attract TAMs and other immune cells to the tumor site." (PMID 40061139, 2025). "Hypoxic environments induce tumor cells and stroma to produce cytokines such as CCL2, CXCL12, CSF1, and VEGF, which recruit macrophages." (PMID 41008931, 2025). "Research evidence indicate that CAFs increase tumor-metastatic characteristics and raise the levels of C-C motif chemokine ligand 2 (CCL2), CCL5, CCL7, CCL26, and CXCL17." (PMID 40869156, 2025). "In line with the CCL2 expression levels, the secretion of CCL2 by tumor cells decreased when treated with 2-DG and increased when treated with NALA." (PMID 39883522, 2025). "During tumorigenesis, inflammatory monocytes from the peripheral blood are attracted to the tumor site by chemokines such as CCL2, as well as cytokines including CSF-1 and VEGF." (PMID 41058699, 2025). "For example, a series of drugs targeting CSF‐1/CSF‐R1 and CCL2/CCR2 signaling pathways have been developed to inhibit TAMs infiltration for anti‐tumor treatment." (PMID 40536254, 2025). "Long non-coding (lnc) RNA increases the release of CCL2 to recruit macrophages in breast cancer BMs, while tumor cell-derived ANXA1 promotes microglial migration." (PMID 40076927, 2025). "Circulating monocytes are instead retained at the CD1a+ stage by GM-CSF, CXCL8, and CCL2 gradients in the primary tumor, turning the pCRC into a functional “monocyte reservoir”." (PMID 41410751, 2025). "The generated IL-12 blocks tumor angiogenesis and induces local tumor necrosis and CCL2, which recruits pDCs to the tumor site for exerting direct cytotoxic activity against tumor cells." (PMID 40547481, 2025). "Overall, the tumor cells’ autonomously enhanced glycolysis and protein lactylation modification upregulate CCL2 expression through the ENSA-K63la/SRC-pS12/STAT3-pY705 axis, thereby recruiting macrophages." (PMID 39883522, 2025). "Among these, CCL2 (or MCP-1), an inflammatory cytokine with multiple roles in promoting immune cell infiltration in the brain and tumor cell migration across the endothelium, was present in high abundance." (PMID 41279931, 2025). "During this process, drug-resistant stem/progenitor-like epithelial populations can stimulate myCAFs to produce CCL2 via soluble mediators (e.g., TNF), thereby recruiting CCR2+ tumor-associated macrophages (TAMs)." (PMID 41514658, 2025). "Here, we identify c-Jun as a central player in DCs mediating the antitumor effect of IMQ through two mechanisms: by controlling tumor angiogenesis via IL-12 expression and pDC recruitment via CCL2." (PMID 39849091, 2025).